RN7SL190P (RNA, 7SL, cytoplasmic 190, pseudogene)
Gene: Miscellaneous RNA gene on chromosome X (123,811,331 to 123,811,587, reverse strand). Ensembl gene ENSG00000264933.
Homologues: Orthologues: macaque Metazoa_SRP (79% identical). Paralogues in human: RN7SL510P (88% identical), RN7SL96P (88% identical), RN7SL134P (87% identical), RN7SL774P (87% identical), Metazoa_SRP (87% identical), RN7SL371P (86% identical), RN7SL163P (86% identical), RN7SL470P (86% identical), RN7SL123P (86% identical), RN7SL488P (86% identical), Metazoa_SRP (85% identical), Metazoa_SRP (84% identical), and 707 more.